HDAC2 (histone deacetylase 2)
Diseases named in the same sentence as HDAC2 in open-access papers (continued):
Sharing a sentence is not in itself a finding about the gene and the disease.
Cerebral ischemia (7 papers, 2018 to 2025). Restriction of arterial blood supply to the brain associated with insufficient oxygenation to support the metabolic requirements of the tissue. "Before quantifying the merged signal, integrated optical density for ATF3 and HDAC2 was measured to confirm their over-expression after brain ischemia." (PMID 37237015, 2023). "After brain ischemia, the increase of HDAC2 levels coincides with the neuronal death, larger ischemic lesions and impaired functional recovery." (PMID 37237015, 2023). "In the subacute phase, the decrease in TOPK levels was accompanied by the down-regulation of M2 surface markers and phosphorylation of HDAC1/HDAC2 following cerebral ischemia-reperfusion in vivo." (PMID 29896413, 2018). "The results of Co-IP showed binding of TOPK to HDAC1 and HDAC2 in brain tissues both under normal conditions and following brain ischemia-reperfusion, with increased binding over time and a significant interaction detected at 3 days for HDAC2." (PMID 29896413, 2018). "HDAC2 knockout enhances neuronal expression of MFN2 and promotes neuronal survival in mice model of cerebral ischemia-reperfusion injury." (PMID 33609088, 2021). "Our proteomics data revealed that the Hdac2 expression levels were dysregulated in rat hippocampal tissues in response to MCAO/R surgery or EA stimulation, suggesting the potential roles of Hdac2 in MCAO/R-induced cerebral damage and EA treatment of cerebral ischemia/reperfusion injury." (PMID 36062010, 2022). "In cerebral ischemia–reperfusion injury, TOPK promotes the polarization of macrophages towards the M2 phenotype, exerting a neuroprotective effect by positively regulating M2 polarization of microglial cells/macrophages through the inhibition of HDAC1/HDAC2 activity." (PMID 40826334, 2025). "Moreover, TOPK co-localized with p-HDAC1 and p-HDAC2 by immunofluorescence, which was confirmed by the Co-IP analysis showing that TOPK binds to HDAC1 and HDAC2 in brain tissues both under normal conditions and following cerebral ischemia-reperfusion." (PMID 29896413, 2018). "Despite the substantial over-expression of both ATF3 and HDAC2 after brain ischemia, only the increase in ATF3 and BCL11B co-expression was observed, while BCL11B and HDAC2 co-expression was not altered, indicating increase of BCL11B was associated with the beneficial processes after brain ischemia." (PMID 37237015, 2023).
emphysema (7 papers, 2011 to 2023). "Similar to previous studies, the expression of ROS, IL‐8, and TNF‐α in our mice exposed to long‐term CS was elevated, which was associated with a reduction in HDAC‐2 activity and emphysema‐like pulmonary destruction." (PMID 34327862, 2021). "A significant reduction in HDAC2 expression was evident in emphysema, exacerbator, and COPD unclassified." (PMID 37373058, 2023). "Emphysema and exacerbator present significant reduction in HDAC2 expression, and only emphysema showed HDAC3 reduction." (PMID 37373058, 2023). "As further evidence that TLR4‐deficiency recapitulates, to some extent, human COPD and CS‐induced emphysema, we found that HDAC2 mRNA expression significantly decreased in lungs from TLR4−/− mice compared to WT." (PMID 30790400, 2019). "In agreement with our results, a recent study demonstrated that a mouse strain highly susceptible to emphysema, showed higher basal level of ROS concurrent with lower levels of Nrf2, HO-1 and HDAC2 compared to an emphysema insensitive-strain." (PMID 21320471, 2011). "Additionally, HDAC2 expression was reduced in patients with emphysema and exacerbator, along with a reduced HDAC3 expression in patients with emphysema." (PMID 37373058, 2023). "We also identify HDAC2 and p16INK4a as potential therapeutic targets for emphysema." (PMID 30790400, 2019). "At least in rats emphysema associated with decreased expression of HDAC2, HIF-1α and VEGF is not due to inflammation." (PMID 23326540, 2013). "Additionally, HDAC2 knockdown enhances the activity of NF-κBp65, thereby increasing IL-8 and TNF-α levels in murine emphysema model." (PMID 34322124, 2021). "In addition, we also observed that in all disease severities and in the emphysema, exacerbator, and unclassified phenotypes, HDAC2 was decreased in both smokers and non-smoker controls, which may contribute to chronic inflammation with subsequent remodeling and airway obstruction." (PMID 37373058, 2023).
endothelial dysfunction (7 papers, 2020 to 2025). In vascular diseases, endothelial dysfunction is a systemic pathological state of the endothelium (the inner lining of blood vessels) and can be broadly defined as an imbalance between vasodilating and vasoconstricting substances produced by (or acting on) the endothelium. "Studies have shown that HDAC2 protects against endothelial dysfunction induced by ox-LDL and that the number of atherosclerotic plaques in mice overexpressing HDAC2 is significantly reduced." (PMID 41403695, 2025). "In endothelial cells, histone deacetylase 2 (HDAC2) protects against endothelial dysfunction and atherogenesis." (PMID 38031118, 2023). "Preventing oxidized LDL-induced HDAC2 downregulation and Arg2 upregulation improves endothelial function, suggesting that HDAC2 could be a novel therapy for inhibiting endothelial dysfunction and AS." (PMID 37298289, 2023).
ischemic stroke (7 papers, 2018 to 2024). A stroke disorder caused by obstruction of blood flow to the brain, due to thrombotic (local blood clot formation) or embolic (due to a blood clot or other material traveling from another site) event. "Other authors also showed the critical role of HDAC2 in death of neurons in the peri-infarction area after ischemic stroke." (PMID 34680562, 2021). "HDAC4 is a unique target for the treatment of ischemic stroke compared with other HDACs, such as HDAC2." (PMID 30208931, 2018). "For example, HDAC4 features different characteristics and plays an opposite role in ischemic stroke compared with HDAC2." (PMID 30208931, 2018). "Within the NVU, ischemic stroke upregulates astrocytic expression of HDAC2 and HDAC8." (PMID 31543756, 2019). "Importantly, reduced HDAC4 expression and increased nuclear shuttling are detected in ischemic stroke model cells and animals, while multiple HDACs, including HDAC2, are increased in ischemic stroke models." (PMID 30208931, 2018). "Although it is inconclusive that increasing HDAC4 expression could offer a better ischemic stroke therapy compared with HDAC2 inhibition, co-regulating HDAC4 and HDAC2 or other HDACs might have better therapeutic potential." (PMID 30208931, 2018). "Moreover, increased HDAC4 expression reduces infarct volume in ischemic stroke model animals and increases cell viability of OGD-treated neurons, while reduced HDAC2 expression promotes neuronal survival and functional recovery in ischemic stroke model animals." (PMID 30208931, 2018). "Hence, HDAC2 was involved in PTS-induced apoptosis in the mouse brain, and its inhibition was beneficial against ischemic stroke." (PMID 34680562, 2021). "In ischemic stroke, the inhibition of both or either HDAC1 and HDAC2 reduce ischemic damage." (PMID 29362442, 2018). "The alteration and function of HDAC4 are opposite to those of HDAC2 in ischemic stroke models, indicating that increasing HDAC4 expression is a unique target for the treatment of ischemic stroke compared with inhibiting HDAC2 and other HDACs to treat ischemic stroke." (PMID 30208931, 2018).
lung adenocarcinoma (7 papers, 2013 to 2023). A carcinoma that arises from the lung and is characterized by the presence of malignant glandular epithelial cells. "The identification of HDAC2's interaction with YY1 in lung adenocarcinoma cells prompted an investigation into the involvement of YY1 in lung adenocarcinoma migration." (PMID 37495623, 2023). "Our additional scrutiny of HDAC2 expression in clinical lung adenocarcinomas corroborated this observation." (PMID 37495623, 2023). "In order to examine the involvement of HDAC2 in the migration of lung adenocarcinoma cells, we conducted an overexpression of HDAC2 in A549 and H441 cells, both are well used KRAS-mutant lung adenocarcinoma." (PMID 37495623, 2023). "Further analysis of the TCGA database demonstrated a marked elevation of HDAC2 expression in lung adenocarcinomas." (PMID 37495623, 2023). "The findings of this investigation unveil a novel role of HDAC2/YY1 in lung adenocarcinoma migration." (PMID 37495623, 2023). "These outcomes provide evidence that YY1 serves as a functional collaborator with HDAC2 in the migration of lung adenocarcinoma cells, and emphasize the potential for targeting HDAC2-YY1 interactions as a means of developing innovative therapeutic approaches." (PMID 37495623, 2023). "This study has provided insight into the heightened expression and induction of HDAC2 during the process of lung adenocarcinoma, which has captured our attention." (PMID 37495623, 2023). "Nevertheless, the precise functional mechanism of HDAC2 in lung adenocarcinoma migration remains elusive, necessitating a comprehensive comprehension of its role in lung adenocarcinoma patients." (PMID 37495623, 2023). "In order to examine the clinical significance of YY1 and HDAC2 in lung adenocarcinoma, we conducted an analysis of their expression levels in clinical patient samples." (PMID 37495623, 2023). "Lungs are always exposed to oxidative stress, and oxidative stress was shown to induce histone acetylation by repression of HDAC2 in the lung adenocarcinoma cell line A549." (PMID 27418136, 2016). "Furthermore, a recent investigation has uncovered the indispensable role of the HDAC2/YY1 complex in lung adenocarcinoma metastasis." (PMID 37495623, 2023). "The present study aimed to examine the involvement of HDACi in TGF-β-mediated cell migration and ascertain the significance of HDAC2 in lung adenocarcinoma cell migration by means of its interaction with YY1 and repression of EMT-related molecule transcriptional activity." (PMID 37495623, 2023). "In order to validate the crucial involvement of YY1 in HDAC2-mediated cellular migration, we conducted a deletion of YY1 in HDAC2 overexpressed lung adenocarcinoma cells." (PMID 37495623, 2023). "Additional competition assays performed in lung adenocarcinoma cell A549 lysate also identified HDAC1, HDAC2, and HDAC6 as targets." (PMID 37322067, 2023). "Nevertheless, a negative correlation was observed between the expression of HDAC2 and the overall survival of lung adenocarcinoma patients, which suggests that HDAC2 may play a role in the advancement of lung adenocarcinoma." (PMID 37495623, 2023).
Obesity (7 papers, 2004 to 2025). Accumulation of substantial excess body fat. "For example, a case control experiment conducted on women with normal weight and women with obesity, showed a differential expression of HDAC2/4/5/6 that could be associated with obesity and inflammatory reactions related to obesity." (PMID 33511131, 2020). "Our data indicate that the obesity impacts on H4ac levels and that strenuous exercise leads to an enhanced chronic low-grade inflammation profile in obesity via an imbalance on H4ac/HDAC2." (PMID 29142617, 2017). "A previous study also demonstrated that HDAC2 contributed to obesity." (PMID 38832038, 2024). "Thus, the decreased HDAC2 activity in obesity may be a potential target for pharmacological or exercise-based therapies." (PMID 29142617, 2017). "However, we cannot exclude the possibility that the activity of HDAC2 might be inhibited in obesity and normalized by CR and RSV." (PMID 26441656, 2015). "The clustering revealed that HDAC2, CEBPB, and EP300 (Cluster 7) were transcriptional regulators for genes dysregulated in obesity and normalized by RSV and CR in both DIO zebrafish and obese human." (PMID 26441656, 2015). "Obesity-related oxidative stress can also suppress key regulatory molecules of corticosteroid sensitivity including phosphoinositide 3-kinase (PI3K) and histone deacetylase 2 (HDAC2)." (PMID 41376865, 2025). "Besides, it has been shown that HDAC2 affected fat accumulation, and a negative correlation existed between HDAC2 and human obesity index." (PMID 38992763, 2024). "Indeed, the binding regions of EP300, CEBPB, and HDAC2 in the promoters of transferrin (TF), insulin-like growth factor binding protein 1 (IGFBP1) and NQO1, whose expression was increased in obesity and was normalized by CR or RSV, overlap." (PMID 26441656, 2015). "However, there is no data about the influence of obesity on H4ac status and HDAC2 activity." (PMID 29142617, 2017).
Sepsis (7 papers, 2010 to 2025). Sepsis is defined as life-threatening organ dysfunction caused by a dysregulated host response to infection. "DEX reduces sepsis-induced AKI by decreasing TNF-α and MCP-1 and increasing BMP-7, which is associated with decreasing HDAC2 and HDAC5, as well as increasing acetyl histone H3." (PMID 40989844, 2025). "The effects of HDAC2 on NETs and sepsis outcomes were investigated using an HDAC2 inhibitor and HDAC2 knockout mice in CLP-induced and LPS-induced sepsis models." (PMID 40850685, 2025). "From our studies we find that epigenetic factors HDAC1, HDAC2 and DNMT3B show consistent differential expression compared to other sepsis cases, suggesting a role in disease susceptibility and pathogenesis." (PMID 28628607, 2017). "DNMT3B, HDAC1 and HDAC2 were significantly up regulated in other sepsis cases compared to healthy controls." (PMID 28628607, 2017). "A recent study showed that decreasing HDAC2 and HDAC5 expression levels were in parallel with increasing acetyl histone H3 and associated with the renoprotective effect of dexmedetomidine in sepsis-induced AKI37." (PMID 27145860, 2016). "PM isolated from IRAK-M−/− mice were largely refractory to CLP-induced impairment in cytokine expression, chromatin remodeling, recruitment of RNA polymerase II, and induction of histone deacetylase-2 observed during sepsis." (PMID 20585389, 2010). "The adoptive transfer of HDAC2 knockdown macrophages attenuates the LPS‐triggered innate inflammatory response in vivo, and these mice are less sensitive to endotoxin shock and Escherichia coli‐induced sepsis." (PMID 30207412, 2019). "While HDAC2 knockout or inhibition reduced inflammation and improved organ function in non-infectious sepsis, it decreased survival in infectious sepsis." (PMID 40850685, 2025). "To this end, we found a selective increase in the expression of HDAC-2 mRNA and protein in CLP PM isolated from WT but not IRAK-M−/− mice LPS has previously been shown to regulate the expression of certain HDACs, although changes in HDAC expression during sepsis have not been defined." (PMID 20585389, 2010).
viral infection (7 papers, 2006 to 2025). "HDACs are implicated in viral infections; for instance, Marek’s disease virus (MDV) interacts with HDAC1 and HDAC2 to facilitate their degradation, while the knockout of HDAC9 enhances foot-and-mouth disease virus (FMDV) replication." (PMID 40938964, 2025). "The colocalization of IE1 with HDAC1 and HDAC2 was also observed in HF cells during the early stage of virus infection." (PMID 25812002, 2015). "It suggests that viral infection might lead to post-translational modifications of HDAC2, which will be investigated in the future." (PMID 34445287, 2021). "Next we determined whether HDAC1/HDAC2 also control CD4+ CTL generation in response to viral infection in vivo." (PMID 32102981, 2020). "Furthermore, like HDAC1, HDAC2 also has been shown to undergo ubiquitination and consequently proteasomal degradation during virus infection as well as heterologous conditions." (PMID 28769891, 2017).
bone cancer (6 papers, 2017 to 2025). A primary or metastatic malignant neoplasm affecting the bone or articular cartilage. "In our previous studies, we identified the modulating effect of HDAC2 in bone cancer pain by utilizing gene-interfering techniques." (PMID 31024248, 2019). "HDAC2 in the spinal cord contributed to mechanical hyperalgesia in a murine model of bone cancer pain." (PMID 31324142, 2019). "Recently, participation of HDAC2 in bone cancer pain and chronic pancreatitis pain was proposed, as a favorable pain-relieving effect was observed after HDAC2 knockdown or inhibition." (PMID 31024248, 2019). "Previous studies reported the same trend of variation in HDAC1 and HDAC2 in bone cancer pain models." (PMID 31024248, 2019). "The reported changes in Hdac2 expression are very complex and controversial in different pain models, including arthritis pain, neuropathic pain, visceral pain, and bone cancer pain." (PMID 38790607, 2024). "Bone cancer caused significantly increased expression of HDAC1 in spinal microglia and neurons, with HDAC2 markedly increased in spinal astrocytes, which were accompanied by the upregulation of MAPK pathways and the activation of microglia and astrocytes in the SDH." (PMID 29096654, 2017). "In a rat model of bone cancer pain, HDAC1 was upregulated in neurons and astrocytes in the dorsal horn, while HDAC2 was upregulated in astrocytes." (PMID 38138971, 2023). "In a rat model of bone cancer pain, HDAC1 was upregulated mainly in neurons and microglia of the spinal dorsal horn, while HDAC2 was upregulated in spinal astrocytes; both enzymes were upregulated in satellite glial cells of the DRG." (PMID 38138971, 2023). "In a rat model of bone cancer pain, HDAC2 was upregulated in the neurons and astroglia but not the microglia of the spinal cord." (PMID 38138971, 2023). "Third, bone cancer induced significant upregulation of MAPK signaling pathways and expression increase of HDAC1 in the microglia and neurons in the SDH as well as remarkable increase of HDAC2 in astrocytes, which were effectively inhibited by T10 treatment." (PMID 29096654, 2017).
breast tumors (6 papers, 2006 to 2024). "For example, class I HDACs have been found to be overexpressed in bladder tumors, breast tumors, prostate tumors, and renal cells, and overexpression of HDAC2 and HDAC3 has also been shown to be associated with clinicopathological indicators of disease progression." (PMID 36371227, 2022). "Breast cell lines showed downregulation of HDAC1, HDAC2, HDAC5, EZH2, EP300, and PCAF compared to breast tumours." (PMID 16638127, 2006). "Survival analyses of OS and RFS showed that the combined expression level of LSD1, HDAC2 and SIRT1 in breast tumors was more predictive for patient survival and tumor relapse than each of the individual markers separately in both univariate and multivariate analyses." (PMID 25139823, 2014). "SIN3B, HDAC1, HDAC2, SUDS3, and RBBP4, but not SIN3A and SAP18, were also upregulated to a lesser degree in human breast tumors." (PMID 37655663, 2023).
cognitive decline (6 papers, 2015 to 2024). "Therefore, there is compelling evidence that HDAC2 is increased in aging and AD, and probably implicated in the associated cognitive decline, although it should be mentioned that a decrease of HDAC2 in AD patients has been also reported by another study." (PMID 26734709, 2015). "HDAC2 downregulation seems to contribute to cholinergic nucleus basalis of Meynert neuronal dysfunction, neurofibrillary tangles pathology, and cognitive decline during the clinical progression of AD." (PMID 36293477, 2022). "For instance, targeting HDAC2 with the specific inhibitor mithramycin improved neuronal plasticity in cellular model of AD, while HDAC6 inhibition improved cognitive decline associated with HD, AD, tauopathy, and Charcot-Marie-Tooth disease." (PMID 33315879, 2020).